ACE (angiotensin I converting enzyme)
Diseases named in the same sentence as ACE in open-access papers (continued):
Sharing a sentence is not in itself a finding about the gene and the disease.
sarcoidosis (continued). "In sarcoidosis granuloma samples, the expression of genes such as ACE and lysozyme (LYZ) is known to be elevated, and these genes were indeed upregulated in TREM2 macrophages." (PMID 38038136, 2023). "The serum ACE level, most commonly used as a biomarker in diagnosing sarcoidosis, in patients with sarcoidosis increases." (PMID 37868968, 2023). "In our case, ACE levels were higher than the normal range (78 IU/L) which provided additional support for a diagnosis of sarcoidosis." (PMID 36789320, 2023). "Hypercalcemia can occur due to vitamin D activation by macrophages in sarcoid granulomas, serum Immunoglobulins are elevated, and serum angiotensin-converting enzyme (ACE) levels are often raised in sarcoidosis patients." (PMID 37273881, 2023). "At the same time, we should clarify the changes of ACE protein level in different types and different stages of sarcoidosis to help us diagnose sarcoidosis and understand its pathogenesis better." (PMID 37868968, 2023). "Elevated ACE levels reportedly occurs in 60–90% of active sarcoidosis, with levels generally proportional to severity." (PMID 35440697, 2023). "Continuous measurement of the serum ACE level can help in monitoring the therapeutic effect in patients with sarcoidosis." (PMID 37868968, 2023). "Serumangiotensin-converting enzyme (ACE) activity was also evaluated in patientssuspected of having sarcoidosis." (PMID 38152007, 2023). "Serum ACE can also reflect the severity of sarcoidosis granulomas and can be used to monitor disease activity and treatment response, with high specificity especially when it’s twice as high as the normal limit." (PMID 37868968, 2023). "Serum biomarkers change with the progress and the improvement of sarcoidosis, so judging the trend of serum biomarkers, such as ACE, is helpful for us to further understand the progress of sarcoidosis, and even make timely therapy before biopsy diagnosis." (PMID 37868968, 2023). "Serum ACE is a commonly used biomarker in diagnosis of sarcoidosis, mainly produced by activated alveolar macrophages." (PMID 37868968, 2023). "Inflectra, which is biosimilar to infliximab, can also be used in the therapy of severe sarcoidosis, with clinical symptoms improved and the serum ACE levels reduced after 26 weeks of Inflectra treatment." (PMID 37868968, 2023). "Most laboratories detect the level of serum ACE, which also increased in other diseases such as tuberculosis and tumor, besides sarcoidosis." (PMID 37868968, 2023). "In healthy individuals, blood ACE levels are very stable over their lifetime, whereas in granulomatous diseases (e.g., sarcoidosis and Gaucher’s disease), blood ACE activity is significantly increased." (PMID 36831070, 2023). "We should take ACE protein level as a serological marker for the diagnosis of sarcoidosis, which has more clinical significance." (PMID 37868968, 2023). "In addition, the level of serum ACE is also affected by ACE gene I/D polymorphism, so clinically, ACE genotypes should be detected first for patients with elevated serum ACE level, and the relationship between elevated serum ACE level and sarcoidosis can be determined according to the ACE genotypes." (PMID 37868968, 2023). "Most studies attest to the fact that ACE and 1,25(OH)2D levels were the most used in juvenile sarcoidosis." (PMID 37108489, 2023). "For instance, higher ACE activity levels have been reported in patients with sarcoidosis but lower levels have been reported in those with fibrosing alveolitis, interstitial lung disease, and chronic obstructive lung disease." (PMID 37108839, 2023). "ACE levels in patients suspected of sarcoidosis can also be influenced by genetic variations and ACE inhibitor therapy." (PMID 36672683, 2023). "Sputum for Acid Fast Bacilli (AFB), sputum for gene Xpert, and Mantoux test were done for TB; and serum Angiotensin Converting Enzyme (ACE) was sent for sarcoidosis." (PMID 37203964, 2023).
sarcoidosis (continued). "Another study showed that among 13 children with probable, presumed, or definite sarcoidosis, 6 patients had elevated ACE levels." (PMID 37721575, 2023). "In healthy individuals, blood ACE levels remain very stable throughout an individual’s lifetime, whereas in granulomatous diseases (e.g., sarcoidosis) and Gaucher’s disease, blood ACE activity is significantly increased." (PMID 36979933, 2023). "On further investigation, angiotensin-converting enzyme (ACE) turned out to be significantly elevated suggesting sarcoidosis." (PMID 38152816, 2023). "It demonstrates that serum ACE vary widely between genotypes, suggesting that clinicians should incorporate exome sequencing in the diagnosis of sarcoidosis to avoid unnecessary invasive biopsies." (PMID 37868968, 2023). "Measurement of serum angiotensin‐converting enzyme (ACE) levels can be helpful in both diagnosis and the monitoring of response to treatment, with raised levels in about 60–80% of patients with sarcoidosis." (PMID 36789320, 2023). "About 30%–80% of patients with sarcoidosis have an elevated serum ACE levels, with a sensitivity of 22%–86% and a specificity of 54%–95%." (PMID 37868968, 2023). "In our study, serum ACE activity was found to be abovethe reference limit (52 IU/L) in 15 (35.7%) of the sarcoidosis patients." (PMID 38152007, 2023). "Other investigations should be chosen case-by-case, for instance, a pregnancy test must be done in all sexually active adolescents, and angiotensin-converting enzyme (ACE) should be measured in the suspicion of sarcoidosis." (PMID 35455555, 2022). "Yet, histopathology and raised angiotensin-converting enzyme (ACE) levels confirmed a diagnosis of sarcoidosis." (PMID 35495013, 2022). "Serological data in patients with sarcoidosis having tumor development showed that serum angiotensin I-converting enzyme (ACE) was significantly reduced at the onset of malignant tumors compared to at the time of diagnosis of sarcoidosis." (PMID 35744031, 2022). "Increased serum/plasma ACE has been reported in other disorders involving activation of the monocyte/macrophage lineage and sarcoidosis is the most frequent and the better studied." (PMID 36544230, 2022). "ACE levels are increased in sarcoidosis because of the activation of monocytes, which are the precursors to the epithelioid cells that form granulomas." (PMID 35669693, 2022). "We found that the serum NSE level was elevated in patients with sarcoidosis and positively correlated with the levels of other traditional markers, including ACE and sIL-2R, suggesting that NSE is a diagnostic marker for sarcoidosis." (PMID 35663496, 2022). "Nonetheless, a clear relationship between sarcoidosis and ACE still has to be drawn, even though a crucial role of ACE in granuloma formation has been supposed, in light of its upregulation in activated macrophages within granulomas." (PMID 36148452, 2022). "Since some reports indicate that sarcoidosis is increasing in frequency, possibly due to industrial contamination, it is likely that accurate quantitative determination of ACE in the blood will be even more clinically useful." (PMID 35996109, 2022). "It was first reported in 1975 when serum ACE levels were observed to increase in active sarcoidosis patients." (PMID 35615369, 2022). "The serum ACE and soluble IL-2 receptor, which reflects the activity of sarcoidosis, showed a decreasing trend in the past-tumor group." (PMID 35744031, 2022). "We performed the combined dosage of angiotensin converting enzyme (ACE) and chitotriosidase, resulted in the normal range excluding the diagnosis of pediatric sarcoidosis." (PMID 36096831, 2022). "Laboratory data of serum NSE, sIL-2R, and ACE were available for sarcoidosis patients who had received OCS therapy due to involvement of organs including the nervous system (N = 7), lung (N = 3), heart (N = 3), kidney (N = 3), skin (N = 2), and spleen (N = 1)." (PMID 35663496, 2022).
sarcoidosis (continued). "Regarding the serological marker when diagnosed with sarcoidosis, serum ACE and soluble Interleukin (IL)-2 receptor tended to be lower in past tumor groups (18.3 ± 5.9 vs. 21.8 ± 13.5, p = 0.061, 782 ± 351 vs. 1093 ± 889, p = 0.072, respectively)." (PMID 35744031, 2022). "Further research is required to determine if high ACE content in sarcoidosis induces the expression level of Ang II and further affects sarcoidosis patients infected with SARS-CoV-2, leading to the progression of sarcoidosis." (PMID 35615369, 2022). "Increased concentrations of serum NSE in patients at the nonremission phase decreased after spontaneous remission, whereas serum NSE levels fluctuated in accordance with serum ACE or sIL-2R levels during the follow-up period in patients with sarcoidosis." (PMID 35663496, 2022). "We found that an increased number of affected organs was associated with elevated serum NSE levels, suggesting that NSE reflects the extent of active granulomatous lesions, as do ACE and sIL-2R, in patients with sarcoidosis." (PMID 35663496, 2022). "Although ACE expression in the serum of sarcoidosis patients is affected by many factors, its sensitivity and specificity are low, and there are genetic polymorphisms in its expression in different populations." (PMID 35615369, 2022). "Elevated levels of ACE and 1,25 Vitamin D levels further support the diagnosis of sarcoidosis in this patient." (PMID 35747109, 2022). "During the diagnostic work-up, elevated angiotensin converting enzyme (ACE) was detected (> 120 U/L), leading to differential diagnosis between sarcoidosis and a lymphoproliferative disorder." (PMID 34996404, 2022). "The results show that sACE is helpful in determining the active status of sarcoidosis, and detection of the decrease in elevated blood ACE is a good marker for efficiency of therapy." (PMID 36291609, 2022). "We first investigated the serum levels of NSE, ACE, sIL-2R, and ProGRP in 114 patients with sarcoidosis." (PMID 35663496, 2022). "Serum levels of angiotensin I-converting enzyme (ACE or CD143) are elevated in many patients with sarcoidosis and initially were thought to parallel the activity of sarcoid lesions." (PMID 35996109, 2022). "As a result, the ACE phenotyping method has the potential add significant value very early in the evaluation process for patients with suspected sarcoidosis." (PMID 35996109, 2022). "The group with proven sarcoidosis (n = 17) presented an ACE level of 46.69 ± 23 IU/L and a lysozyme level of 43± 67 mg/L." (PMID 33805490, 2021). "We also confirmed elevated circulating ACE levels in patients with sarcoidosis and proposed that it can be used as a biomarker for sarcoidosis." (PMID 34359878, 2021). "A history of sarcoidosis, a positive serum ACE, or appropriate chest X-ray findings can raise breast sarcoidosis suspicions." (PMID 33608057, 2021). "Although uveitis and high levels of ACE and sIL-2R suggested sarcoidosis, concern about infectious disease remained according to the necrotizing granuloma of pathological findings." (PMID 33865452, 2021). "The angiotensin-converting enzyme (ACE) level was evaluated for sarcoidosis, and was found to be normal." (PMID 34030739, 2021). "Serum levels of ACE were increased in the large majority, although the specificity and sensitivity of a high ACE level for the diagnosis of sarcoidosis are only 90% and 41%, respectively." (PMID 32740881, 2020). "ACE levels above 50% of the upper normal limit are indeed considered abnormal but cannot be sufficient to provide a suspicion of sarcoidosis; other tests are thus needed." (PMID 32962242, 2020). "In sarcoidosis patients, chitotriosidase activity and ACE concentrations were directly correlated (r = 0.34, p<0.0001)." (PMID 31906975, 2020). "For example, B-cell activating factor (BAFF) levels are elevated in patients with sarcoidosis and are correlated with ACE levels." (PMID 33330555, 2020).
sarcoidosis (continued). "In sarcoidosis patients, chitotriosidase showed higher sensitivity and specificity than other biomarkers, including angiotensin converting enzyme (ACE), lysozyme and soluble IL-2 receptor." (PMID 31906975, 2020). "More recently, a soluble form of the IL-2 receptor (sIL-2R) which is secreted by T-cells upon activation, has shown promise as a more sensitive and specific marker for sarcoidosis compared to traditional tests such as ACE and lysozyme." (PMID 33036432, 2020). "Among these three major forms of uveitis, biomarkers such as sIL-2R and ACE were found only in sarcoidosis [12.13]." (PMID 33291298, 2020). "Elevated serum levels of ACE have been intensively studied since 1975 and this is currently the most frequently used laboratory test in sarcoidosis." (PMID 32760396, 2020). "While increased CTO is not specific for sarcoidosis, the enzyme has proven to be a very sensitive biomarker of active sarcoidosis and has more sensitivity and specificity than other commonly used sarcoid biomarkers such as ACE and lysozyme." (PMID 33036432, 2020). "If patients with sarcoidosis use ACE inhibitors, serum ACE levels cannot be used in diagnosis or disease monitoring, and should be interpreted carefully." (PMID 32760396, 2020). "Traditionally used markers of sarcoidosis such as Angiotensin Converting Enzyme (ACE) and lysozyme—enzymes produced by granuloma macrophages—display low sensitivity and/or specificity." (PMID 33036432, 2020). "We also demonstrated the presence of conformationally-altered ACE in blood of patients with sarcoidosis, uremia or Gaucher disease." (PMID 31877149, 2019). "In sarcoidosis, KL-6 correlates with ACE activity: it is mainly increased in stage 2 and 3 patients with scintigraphic evidence of positive pulmonary accumulation." (PMID 30944672, 2019). "Serum angiotensin-converting enzyme (ACE) and soluble interleukin-2 receptor (sIL-2R) are useful for evaluating sarcoidosis disease activity." (PMID 31515495, 2019). "Positive correlations were detected among sarcoidosis biomarkers, including ACE, lysozyme, chitotriosidase, and KL-6 that can therefore be included in the list of prognostic indicators." (PMID 30944672, 2019). "Our study, using robust and frequently used statistical methods such as the C-statistic and Youden’s index, demonstrates that serum sIL-2R is more sensitive and equally specific as ACE in diagnosis in patients suspected of sarcoidosis." (PMID 31622413, 2019). "In healthy individuals, the concentration of ACE in blood is stable, but is significantly increased in subjects with either sarcoidosis or Gaucher disease (3 to 5-fold increase in blood) serving as a potential clinical biomarker of disease severity." (PMID 31877149, 2019). "CD69 expression levels were significantly correlated with ACE and sIL-2R levels, which are markers of clinical sarcoidosis disease activation." (PMID 31515495, 2019). "But in this case, we have also seen elevated levels of serum ACE which dropped significantly to the normal level along with a complete clearance of lesions with systemic steroids, and this favours sarcoidosis." (PMID 30026760, 2018). "Multivariate analysis revealed an association between the presence of active sarcoidosis and the levels of hs-CRP (OR = 5.162, p = 0.002) and ACE (OR = 1.085, p = 0.029)." (PMID 30154391, 2018). "Sputum smear, culture, and PCR were performed to test for TB, and angiotensin-converting enzyme (ACE) levels were measured for sarcoidosis." (PMID 29904593, 2018). "In hilar lymphadenopathy of lung, sarcoidosis is an importance differential diagnosis that should be considered and prior to biopsy of lymph nodes and any invasive procedures, ACE enzyme levels should be measured." (PMID 29904593, 2018). "We aimed to investigate the diagnostic features of YKL-40, sIL-2R, ACE, hs-CRP, neopterin concentrations and ADA markers in active and inactive discrimination of sarcoidosis disease." (PMID 30154391, 2018).
sarcoidosis (continued). "The best-known marker is ACE activity in sarcoidosis that ACE activities were elevated in active sarcoidosis patients compared to inactive patients in current study." (PMID 30154391, 2018). "Clinical disease activity has been correlated with serum ACE, lysozyme and sIL-2R in patients with sarcoidosis." (PMID 30154391, 2018). "Increased ACE expression in pulmonary granulomas in sarcoidosis has long been recognized, and elevations in ACE have been reported in IPF." (PMID 29202450, 2017). "Serum ACE level has been compared between patients having sarcoidosis and sarcoidosis-like lung diseases including TB, fibrosing alveolitis, histiocytosis X, and pneumoconiosis." (PMID 26879979, 2016). "The levels of at least one of the serum markers ACE and lysozyme were found elevated in 58 % of patients with biopsy-proven sarcoidosis." (PMID 26879979, 2016). "Our study revealed a statistically significant difference in serum ACE level for patients with presumed sarcoidosis compared to patients with AS (p = 0.0001)." (PMID 26879979, 2016). "The serum activity of ACE has been compared for patients with BD, Vogt-Koyanagi-Harada’s disease and sarcoidosis." (PMID 26879979, 2016). "The sensitivity of serum lysozyme for predicting sarcoidosis was reported as 79.1 % and the sensitivity of serum ACE for predicting sarcoidosis was reported as 59 %." (PMID 26879979, 2016). "A significant elevation of serum ACE level in patients with presumed sarcoidosis with respect to BD has been disclosed in our study (p = 0.0001)." (PMID 26879979, 2016). "The increase in serum ACE level was significant for patients with presumed sarcoidosis compared to patients with AS (p = 0.0001), BD (p = 0.0001), presumed latent TB (p = 0.0001), presumed latent syphilis (p = 0.0001), and control group (p = 0.0001)." (PMID 26879979, 2016). "Serum angiotensin converting enzyme (ACE) is probably the most common laboratory test for sarcoidosis, revealing an approximate sensitivity of 57–73% and a specificity of 90% in the literature, but only 22% sensitivity and 90% specificity in our patients." (PMID 26799486, 2016). "Pairwise comparison of serum ACE levels between patients with presumed latent TB and presumed sarcoidosis disclosed a statistically significant difference for patients with presumed sarcoidosis with respect to presumed latent TB (p = 0.0001)." (PMID 26879979, 2016). "Mean ACE value was 59 U/ml in the sarcoidosis patients with uveitis (n = 41) while that of the uveitis patients without sarcoidosis (n = 220) was just 35 U/ml (p<0.001)." (PMID 26799486, 2016). "In our second patient, to exclude pheochromocytoma, mast cell disorders, and sarcoidosis, vanillylmandelic acid levels in 24-hour urine, blood tryptase level, ACE, and 25-OH vitamin D levels were studied and determined to be within normal levels." (PMID 27413567, 2016). "Members of the international Workshop on Ocular Sarcoidosis recommended elevated serum angiotensin converting enzyme (ACE), elevated serum lysozyme and abnormal liver enzyme tests." (PMID 26799486, 2016). "To better understand the associations between the Treg/Th17 ratio and clinical indices in sarcoidosis relapse patients, we assessed several useful indices, including serum ACE and FEV1% and DLco% predicted values." (PMID 26845566, 2016). "In further support of a diagnosis of sarcoidosis, angiotensin converting enzyme (ACE) level was elevated to 73 U/L (normal 8–52 U/L)." (PMID 28031822, 2016). "Human AM are also known to contain ACE, and the mononuclear phagocyte cell line is considered the primary source of serum ACE in sarcoidosis." (PMID 27275272, 2015). "Physical examination and investigations pointed toward sarcoidosis, including raised erythrocyte sedimentation rate, angiotensin converting enzyme (ACE), and alanine transaminase (ALT)." (PMID 26442237, 2015).